PARP1 (poly(ADP-ribose) polymerase 1)
Diseases named in the same sentence as PARP1 in open-access papers (continued):
Sharing a sentence is not in itself a finding about the gene and the disease.
cardiac hypertrophy (continued). "In this regard, it is assumed that Nor1 upregulates the expression of hypertrophy markers and additionally promotes PARP-1 activation, resulting in functional impairment and progression of cardiac hypertrophy and heart failure." (PMID 33927770, 2021). "PARP1 overactivation plays a pivotal role in transformation of pathological cardiac hypertrophy to heart failure." (PMID 33482196, 2021). "Cardiac hypertrophy is an important stage of heart failure development, and PARP-1 has been shown to be critical for the development of cardiac hypertrophy." (PMID 32139662, 2020). "Our results indicate that SIRT3 exerts protective effects against cardiac hypertrophy by reducing the level of acetylation and activity of PARP-1, thus providing novel mechanistic insights into SIRT3-mediated cardiprotective actions." (PMID 32139662, 2020). "Poly [ADP-ribose] polymerase 1 (PARP-1) functions as an important PARP isoform that was involved in cardiac hypertrophy." (PMID 32139662, 2020). "Furthermore, during myocardial remodeling processes, ubiquitination-mediated degradation of poly (ADP-ribose) polymerase 1 (PARP-1) was found to attenuate apoptotic damage, thereby alleviating pathological cardiac hypertrophy and heart failure development." (PMID 40421455, 2025). "Similar results were observed in PARP1-induced cardiac hypertrophy." (PMID 35002525, 2022). "In this study, we found C/EBPβ participates in PARP1-induced cardiac hypertrophy." (PMID 35002525, 2022). "Finally, cardiac-specific C/EBPβ mutant K134A or mutant ΔSUMO mice would unambiguously address questions about the roles of C/EBPβ and PARP1 in the process of cardiac hypertrophy." (PMID 35002525, 2022). "To explore the mechanisms by which C/EBPβ participates in PARP1-induced cardiac hypertrophy, we hypothesized that PARP1 might interact with C/EBPβ and PARylate it." (PMID 35002525, 2022). "Considering that C/EBPβ activity/expression and PARP1 activity (PARylation) were both augmented in cardiac hypertrophy, we further explored whether the change of C/EBPβ was associated with PARP1." (PMID 35002525, 2022). "It is worth noting whether SUMO1 was indispensable in PARP1-induced hypertrophy responses, and the crosstalk between the two PTMs in cardiac hypertrophy drew our full attention." (PMID 35002525, 2022). "Whether or not the specific site of PARylation affects other post-translational modifications, and whether other modifications participate in PARP1-induced cardiac hypertrophy remain largely undetermined." (PMID 35002525, 2022). "PARP-1 is involved in the pathological mechanism of cardiac hypertrophy and heart failure." (PMID 34776960, 2021). "PARP-1 activation induces cardiac hypertrophy mainly by catalyzing the transfer of ADP-ribose from nicotinamide adenine dinucleotide (NAD+) to its target protein, consuming intracellular NAD+, impairing energy metabolism, and causing decreased activity of type III histone deacetylase (SIRTs)." (PMID 32139662, 2020). "Similarly, in myocardial hypertrophy, PARP1 upregulated STAT3 transcriptional activity by retaining phosphorylated-STAT3 in the nucleus independently of JAK2 activation." (PMID 32900001, 2020). "Likewise, PARP-1 inhibitor L-2286 significantly attenuated cardiac hypertrophy induced by pressure overload." (PMID 32139662, 2020). "In addition to HDACs, PARP1 is the only other chromatin-modifying enzyme known to regulate cardiac hypertrophy." (PMID 30792806, 2018). "Importantly, Inhibition of PARP1 by genetic deletion or treatment with a chemical antagonist had protective effects against cardiac hypertrophy and LV dysfunction in chagasic heart." (PMID 29851986, 2018). "PARP-1 is known to be involved in diseases like hypertension and inflammation, although PARP-1 deficient mice do not develop cardiac hypertrophy." (PMID 22200760, 2012). "Furthermore, C/EBPβ K134 site SUMOylation could decrease C/EBPβ protein stability and participates in PARP1-induced cardiac hypertrophy." (PMID 35002525, 2022).
cardiac hypertrophy (continued). "Importantly, C/EBPβ K134 site SUMOylation could decrease C/EBPβ protein stability and participates in PARP1-induced cardiac hypertrophy." (PMID 35002525, 2022). "Interestingly, PARP1 increase in cardiovascular diseases such as cardiac hypertrophy." (PMID 33916982, 2021). "Therefore, SIRT3/PARP-1 pathway regulation may represent a promising tool for improving mitochondrial function and treating cardiac hypertrophy." (PMID 34776960, 2021). "However, no report is available as to whether SIRT3 can interact and deacetylate PARP-1 and thereby ameliorating cardiac hypertrophy." (PMID 32139662, 2020). "In the signaling pathway of cardiac hypertrophy, BAF55 suppresses ubiquitin-protein ligase WWP2-mediated PARP1 ubiquitination." (PMID 39865120, 2025). "The poly (ADP-ribose) polymerases (PARPs) family members such as PARP-1 and PARP-2 has been revealed to participate in the progression of cardiac hypertrophy due to different cellular localization and regulating mechanisms." (PMID 37219631, 2023). "In summary, the present study provides evidence that quercetin ameliorates cardiac hypertrophy by protecting mitochondrial structure and function in SHRs and Ang II-induced H9c2 cells, involving the SIRT3/PARP-1 pathway." (PMID 34776960, 2021). "The purpose of this study was to confirm that quercetin alleviated cardiac hypertrophy, focusing on the SIRT3/PARP-1 pathway both in spontaneously hypertensive rats (SHRs) and H9c2 cells." (PMID 34776960, 2021). "Our previous studies have shown that PARP-1 activity was significantly up-regulated in cardiac hypertrophy, while inhibition of PARP-1 activity can significantly inhibit cardiac hypertrophy." (PMID 32139662, 2020). "In the cardiac hypertrophy model of ISO-stimulated SD rats, the interaction between SIRT3 and PARP-1 was enhanced, whereas the level of acetylation of PARP-1 was also increased." (PMID 32139662, 2020). "PARP-1 inhibitor and PARP-1 knockdown can inhibit angiotensin II (AngII)-induced cardiac hypertrophy." (PMID 32139662, 2020). "In the ISO-induced in vivo cardiac hypertrophy model, nucleoproteins of heart tissues were extracted, and SIRT3 and PARP-1 interactions were also detected by CO-IP." (PMID 32139662, 2020). "PARP-1 is involved in regulating blood pressure and inflammatory processes, but PARP-1-deficient mice do not develop cardiac hypertrophy." (PMID 40358169, 2025). "NOR1 may also be involved in the process of isoprenaline-induced cardiac hypertrophy by regulating poly ADP-ribose polymerase-1 (PARP-1), and silencing of the NOR1 gene ameliorates neosynephrine-induced cardiac hypertrophy." (PMID 36110555, 2022). "In addition, in the cardiac hypertrophy model of ISO-induced SD rats, the activity of PARP-1 was also significantly up-regulated compared with the control group." (PMID 32139662, 2020). "To investigate whether SIRT3 inhibits cardiac hypertrophy by inhibiting PARP-1 activity, we overexpressed SIRT3 in cardiomyocytes with Ad-SIRT3, then stimulate with ISO or PE for 24 h, and detect PARP-1 activity changes with anti-PAR antibody." (PMID 32139662, 2020). "Based on the fact that both SIRT3 and PARP-1 consume NAD+ to exert their functions, we hypothesized that SIRT3 could inhibit cardiac hypertrophy by repressing PARP-1 activation in cardiomyocytes." (PMID 32139662, 2020). "Taken together, the results above suggest that PARP1 could induce cardiac hypertrophy and positively regulate C/EBPβ protein level without affecting its transcription level, which imply C/EBPβ may participate in PARP1-induced cardiac hypertrophy." (PMID 35002525, 2022).
heart failure (26 papers, 2014 to 2025). Inability of the heart to pump blood at an adequate rate to meet tissue metabolic requirements. "This action suppresses the excessive PARP1 activity and PARylation that drive myocardial hypertrophy and fibrosis, revealing a novel therapeutic axis for heart failure." (PMID 41362701, 2025). "Conversely, TGP decreased the expression of PARP-1 and NF-κB, indicating that the anti-heart failure action of TGP is mediated by modulation of the PARP-1 and the NF-κB signaling pathway." (PMID 37831380, 2024). "In summary, our findings elucidate the significance of PARP1 in heart regeneration, indicating a promising therapeutic target for preventing heart failure after cardiac injury." (PMID 38481797, 2024). "In addition, in the tissue biopsy of heart failure, since the increase of active oxygen and oxygen free radicals, the expression and activity of PARP1 are increased." (PMID 38169534, 2024). "The prominent role of PARP1 in experimental AF progression thus extends previous observations in models of other cardiovascular disease, including heart failure models in mice, dogs, and rats, where activation of PARP1-induced endothelial dysfunction, myocardial hypertrophy, and remodeling." (PMID 30898999, 2019). "Importantly, previous studies in biopsy material from patients with heart failure reported increased expression and activation of PARP1 to contribute to disease progression." (PMID 30898999, 2019). "This cleavage of PARP1 producing 25 and 89 kDa fragments is mediated by executioner caspases csp-3 and csp-7 expression of which was unchanged or decreased depending on the type of heart failure." (PMID 28454582, 2017). "In addition, PARP1 inhibition has been demonstrated to provide protection against endothelial dysfunction in shock, hypertension, and heart failure." (PMID 25412407, 2015). "Therefore, PARP1 inhibition was proved to be cardiac-protective in heart failure and post-infarction myocardial remodeling, but whether it is involved in MIRI is unknown." (PMID 34124031, 2021). "In sepsis‐induced cardiac injury and heart failure, the E3 ubiquitin ligase WWP2 protects against cardiac remodeling by targeting poly (ADP‐ribose) polymerase‐1 (PARP1) for ubiquitination and proteasomal degradation." (PMID 41362701, 2025). "In myocardium, PARP-1 was reported to promote myocardial remodeling, and increased PARP-1 activity led to heart failure in mice and humans." (PMID 36093141, 2022). "Moreover, the study revealed that SDSL, via the regulation of PARP1 under ISO induction, plays a pivotal role in promoting the development and progression of heart failure in patients." (PMID 38250028, 2023). "However, in Ang II-induced heart failure, the expressions of α-SMA, Col-1, cleaved-Caspase3, and cleaved-PARP1 were obviously declined after NALA administration." (PMID 37443257, 2023). "Therefore, we suggested that ISO induced SDSL expression promotes cardiomyocyte apoptosis by regulating PARP1, thereby promoting the progress of heart failure, and confirms that SDSL is a factor promoting heart failure." (PMID 38250028, 2023).
osteosarcoma (26 papers, 2014 to 2025). A usually aggressive malignant bone-forming mesenchymal neoplasm, predominantly affecting adolescents and young adults. "GSEA analysis showed that PARP1/2 was associated with osteosarcoma cell cycle, and we evaluated the effect of olaparib on the cell cycle of osteosarcoma cells." (PMID 38213724, 2024). "Ezrin, a protein reported closely associated with osteosarcoma metastasis, was confirmed to be an interactive protein for PARP1." (PMID 35173550, 2022). "As a hallmark of apoptosis, we searched for cleaved PARP-1 after MEK6 silencing in two osteosarcoma cell lines (HOS and KHOS/NP) treated with pazopanib + trametinib combination." (PMID 32531992, 2020). "Increased apoptosis of osteosarcoma cells by co-treatment of olaparib and doxorubicin was associated with increased expression of cleaved PARP1, cleaved caspase 3, and BAX, and decreased expression of BCL2." (PMID 29784019, 2018). "In osteosarcoma tissue samples, the expression of PARP1 and the molecules related with the response of PARP1 to DNA damage were significantly associated with shorter survival of osteosarcoma patients." (PMID 29784019, 2018). "Besides, it could also be possible that PARP1-Ezrin axis is relatively more dominant in osteosarcoma compared to other signaling pathways associated with cell migration and metastasis." (PMID 35173550, 2022). "The adipocytes secret A1BG and stabilize NAMPT, leading to increased NAD+ levels and subsequent increased PARP1‐mediated DNA repair, resulting in cisplatin resistance in osteosarcoma finally." (PMID 40560034, 2025). "Collectively, our results identify A1BG as a critical adipocyte‐derived protein that mediates cisplatin resistance in osteosarcoma by promoting PARP1/ATM‐dependent DNA repair." (PMID 40560034, 2025). "Our study reveals that A1BG overexpression is a universal characteristic of adipocytes, and CAAs similarly induce cisplatin resistance in osteosarcoma through the A1BG/NAMPT/PARP1 axis." (PMID 40560034, 2025). "Targeting this pathway using NAMPT or PARP1 inhibitors represents a promising therapeutic strategy to overcome chemoresistance in osteosarcoma." (PMID 40560034, 2025). "Knockdown of PARP1 has been found to inhibit proliferation and increase chemotherapy sensitivity to doxorubicin in osteosarcoma cells." (PMID 40283955, 2025). "To validate our findings in a clinically relevant setting, we first assessed the effects of NAMPT and PARP1 inhibition in patient‐derived osteosarcoma organoids." (PMID 40560034, 2025). "Our study provides novel evidence that adipocytes contribute to cisplatin resistance in osteosarcoma by activating the A1BG/NAMPT/PARP1 axis." (PMID 40560034, 2025). "Specifically, osteosarcoma cells treated with 2 displayed phosphatidylserine residues on their cell membrane exterior and an increase in cleaved caspase 3 and 7 and PARP‐1 levels, implicative of caspase‐dependent apoptosis." (PMID 40202773, 2025). "Taken together, these findings demonstrate that adipocyte‐derived A1BG promotes cisplatin resistance in osteosarcoma by activating the NAMPT/PARP1 pathway." (PMID 40560034, 2025). "We discovered that PARP1 interacted with a protein playing a crucial role in osteosarcoma metastasis - ezrin and regulated its phosphorylation." (PMID 35173550, 2022). "When the U2OS and KHOS/NP osteosarcoma cells were treated with doxorubicin, the expression of cleaved PARP1, cleaved caspase 3, and BAX increased, and the expression of BCL2 decreased." (PMID 34359939, 2021). "Under doxorubicin treatment of U2OS and KHOS/NP osteosarcoma cells, the expression levels of cleaved PARP1, cleaved caspase 3, and BAX increased, and the expression of BCL2 decreased with the knock-down of CSNK2A1." (PMID 34359939, 2021). "The possible role of PARP1 in the chemosensitization of NMNAT1−/− osteosarcoma cells was also supported by previous preclinical studies." (PMID 32392755, 2020).
osteosarcoma (continued). "PARP1, γH2AX, BRCA1, and BRCA2 are found in the nuclei of osteosarcoma tumours, and poor survival in osteosarcoma patients has been linked to expression of these factors." (PMID 32961800, 2020). "High PARP1 expression in osteosarcoma has also been correlated with shorter survival, suggesting a role for this BER protein in resistance as well." (PMID 32961800, 2020). "The expression patterns of PARP1, γH2AX, BRCA1, and BRCA2 were significantly associated with shorter survival of osteosarcoma patients." (PMID 29784019, 2018). "In human osteosarcoma tissues, the expression of PARP1 and γH2AX were observed in the nuclei of tumor cells." (PMID 29784019, 2018). "In osteosarcoma cells, knock-down of PARP1 and treatment of olaparib significantly inhibited proliferation of cells and induced apoptosis." (PMID 29784019, 2018). "The expression of PARP1 showed borderline significance for the survival of low-grade osteosarcoma patients (OS; P = 0.067, RFS; P = 0.055)." (PMID 29784019, 2018). "Supportively, single uses of the PARP inhibitor olaparib and knock-down of PARP1 with siRNA significantly inhibited proliferation of osteosarcoma cells in a dose- and time-dependent manner." (PMID 29784019, 2018). "As was shown with the co-treatment of olaparib and doxorubicin, the knock-down of PARP1 with siRNA for PARP1 also potentiates the anti-cancer effects of doxorubicin in osteosarcoma cells." (PMID 29784019, 2018). "The variables included in multivariate analysis for the 35 osteosarcomas were the factors significantly associated with OS or RFS: age, tumor size, tumor stage, distant metastasis, histologic grade, and the expression of PARP1, γH2AX, BRCA1, and BRCA2." (PMID 29784019, 2018). "This study has also shown that the expression of PARP1, γH2AX, BRCA1/2 are significantly associated with RFS of osteosarcoma patients." (PMID 29784019, 2018). "We hypothesized that A1BG stimulates NAMPT activity, leading to increased NAD+ levels and subsequent activation of PARP1, thereby promoting DNA repair and contributing to cisplatin resistance in osteosarcoma." (PMID 40560034, 2025). "Moreover, co-treatment of siRNA for PARP1 and doxorubicin stimulated apoptotic signaling of osteosarcoma cells as indicated by an increase of cleaved PARP1 and BAX and a decrease of BCL2 expression." (PMID 29784019, 2018). "Moreover, inhibition of PARP1 with either olaparib or siRNA induced apoptosis of osteosarcoma cells and potentiated the cytotoxic effects of doxorubicin." (PMID 29784019, 2018). "However, despite extensive assessment of the role of PARP1 as a prognostic marker and therapeutic target of various human malignant tumors, there are limited reports focused on osteosarcoma." (PMID 29784019, 2018). "Based on this rationale, this study might also be helpful for the selection of osteosarcoma patients that could potentially benefit from anti-PARP therapy, especially those in the poor-prognostic subgroup of osteosarcomas expressing PARP1, γH2AX, or BRCA1/2." (PMID 29784019, 2018). "In addition, co-treatment of siRNA for PARP1 and doxorubicin significantly inhibited the proliferation of osteosarcoma cells compared with individual treatment of siRNA for PARP1 or doxorubicin." (PMID 29784019, 2018). "In this study, we have shown that PARP1-targetted therapy might be helpful in the treatment of osteosarcoma patients." (PMID 29784019, 2018). "In clinical tissue samples, the expression of PARP1, γH2AX, BRCA1, and BRCA2 were closely associated with each other and their expression patterns were correlated with advanced clinical indicators of osteosarcoma such as higher stage, latent distant metastasis, and higher histological grade." (PMID 29784019, 2018).